IGHV3-21 (immunoglobulin heavy variable 3-21)
Description:
V region of the variable domain of immunoglobulin heavy chains that participates in the antigen recognition. Immunoglobulins, also known as antibodies, are membrane-bound or secreted glycoproteins produced by B lymphocytes. In the recognition phase of humoral immunity, the membrane-bound immunoglobulins serve as receptors which, upon binding of a specific antigen, trigger the clonal expansion and differentiation of B lymphocytes into immunoglobulins-secreting plasma cells. Secreted immunoglobulins mediate the effector phase of humoral immunity, which results in the elimination of bound antigens. The antigen binding site is formed by the variable domain of one heavy chain, together with that of its associated light chain. Thus, each immunoglobulin has two antigen binding sites with remarkable affinity for a particular antigen. The variable domains are assembled by a process called V-(D)-J rearrangement and can then be subjected to somatic hypermutations which, after exposure to antigen and selection, allow affinity maturation for a particular antigen.
Synonyms: IGHV321; VH
Gene: Immunoglobulin variable (V) gene on chromosome 14 (106,235,064 to 106,235,594, reverse strand). Ensembl gene ENSG00000211947.
Subcellular location: Secreted; Cell membrane
Gene Ontology:
Molecular function: antigen binding
Biological process: immunoglobulin mediated immune response
Cellular component: extracellular region; plasma membrane
Homologues: Paralogues in human: IGHV3-48 (95% identical), IGHV3-11 (89% identical), IGHV3-7 (89% identical), IGHV3-74 (87% identical), IGHV3-23 (86% identical), IGHV3-13 (85% identical), IGHV3-66 (85% identical), IGHV3OR16-10 (85% identical), IGHV3-64 (84% identical), IGHV3OR16-13 (84% identical), IGHV3-30 (83% identical), IGHV3-33 (83% identical), and 65 more.